MC1R (melanocortin 1 receptor)
Description:
G protein-coupled receptor that binds melanocyte-stimulating hormones (alpha, beta, and gamma-MSH) and adrenocorticotropic hormone/ACTH, which are peptide products of the POMC precursor protein. Upon activation, MC1R couples with the G(s) protein, stimulating adenylate cyclase and activating the cAMP-dependent signaling pathway. This activation promotes melanogenesis, resulting in the production of eumelanin (black/brown) and pheomelanin (red/yellow) in melanocytes. MC1R interacts with G protein-coupled receptor opsin 3/OPN3, which couples to G(i) proteins and inhibits the alpha-MSH-induced cAMP response, thereby reducing melanin synthesis. Binding to Agouti/ASP precludes alpha-MSH-induced signaling, thereby downregulating melanogenesis (By similarity). Additionally, interaction with MGRN1 displaces the G(s) protein, further suppressing MC1R signaling.
Synonyms: MSH-R; CMM5; SHEP2
Tractability: Small molecule: a drug acting on it is in phase 2 or 3 trials; a high-quality ligand is known; it belongs to a druggable protein family. Antibody: UniProt places it where antibodies can reach, with high confidence; its Gene Ontology location is reachable by antibodies, with high confidence; UniProt predicts a signal peptide or a membrane-spanning region. PROTAC: ubiquitination databases record sites on it; a small molecule that binds it is known. Other modalities: an approved drug acts on it.
Target class: Short peptide receptor (family A GPCR); Peptide receptor (family A GPCR); Melanocortin receptor; Membrane receptor; Family A G protein-coupled receptor
Chemical probes: (D-Phe7)-?-MSH (trifluoroacetate salt), CHEMBL218748, CHEMBL275067, CHEMBL3601432
Gene: Protein-coding gene on chromosome 16 (89,912,119 to 89,920,977, forward strand). Ensembl gene ENSG00000258839.
Subcellular location: Cell membrane
Pathways (Reactome):
Signal Transduction: G alpha (s) signalling events; Peptide ligand-binding receptors
Developmental Biology: Transcriptional and post-translational regulation of MITF-M expression and activity
Gene Ontology:
Molecular function: corticotropin receptor activity; melanocyte-stimulating hormone receptor activity; protein binding; ubiquitin protein ligase binding; G protein-coupled peptide receptor activity; melanocortin receptor activity; G protein-coupled receptor activity; hormone binding
Biological process: adenylate cyclase-activating G protein-coupled receptor signaling pathway; negative regulation of tumor necrosis factor production; positive regulation of melanin biosynthetic process; UV-damage excision repair; G protein-coupled receptor signaling pathway, coupled to cyclic nucleotide second messenger; intracellular signal transduction; melanin biosynthetic process; phospholipase C-activating G protein-coupled receptor signaling pathway; pigmentation; positive regulation of cAMP/PKA signal transduction; positive regulation of transcription by RNA polymerase II; UV protection; G protein-coupled receptor signaling pathway; neuropeptide signaling pathway; positive regulation of feeding behavior; regulation of feeding behavior; regulation of gene expression
Cellular component: plasma membrane; cytoplasm; membrane
Genetic constraint (gnomAD): Loss-of-function variants: 4 observed, 2.6 expected, observed/expected ratio (o/e) 1.54, 90% interval 0.65 to 1.93. That is too few expected variants to judge how well the gene tolerates losing a copy. Missense variants: 536 observed, 423.97 expected, observed/expected ratio (o/e) 1.26, 90% interval 1.18 to 1.36. Synonymous variants: 262 observed, 198.64 expected, observed/expected ratio (o/e) 1.32, 90% interval 1.19 to 1.46.
Homologues: Orthologues: macaque MC1R (92% identical), pig MC1R (79% identical), rat Mc1r (79% identical), rabbit MC1R (78% identical), guinea pig MC1R (77% identical), mouse Mc1r (76% identical), zebrafish mc1r (55% identical), tropical clawed frog mc1r (50% identical). Paralogues in human: MC4R (47% identical), MC3R (46% identical), MC5R (44% identical), MC2R (37% identical), GPR12 (27% identical), GPR6 (26% identical), S1PR2 (26% identical), GPR3 (24% identical), CNR1 (23% identical), LPAR1 (23% identical), S1PR1 (23% identical), S1PR3 (22% identical), and 6 more.
Diseases named in the same sentence as MC1R in open-access papers:
MC1R is named in the same sentence as 181 diseases in open-access papers, as found by Europe PMC text mining. Sharing a sentence is not in itself a finding about the gene and the disease. The quoted sentences say what the papers report.
melanoma (395 papers, 2002 to 2026). A malignant, usually aggressive tumor composed of atypical, neoplastic melanocytes. "For instance, the S-palmitoylation of MC1R, which involves the covalent attachment of palmitic acid to cysteine residues on the protein, enhances its activity and has been linked to reduced melanoma development in mice." (PMID 41596686, 2026). "MC1R R-alleles, associated with red hair, fair skin and increased melanoma risk, were less frequent than in adult cases (0.46 vs. 0.64)." (PMID 41673532, 2026). "These individuals frequently carry MC1R polymorphisms, which not only reduce eumelanin production but also impair DNA repair mechanisms, further amplifying melanoma risk." (PMID 40507265, 2025). "First, genetic variants of the melanocortin-1 receptor (MC1R), which affect pigmentation traits, significantly increase melanoma risk, both independently of skin phototype and in combination with other risk alleles (e.g., CDKN2A mutations)." (PMID 41011113, 2025). "Studies conducted before the introduction of ICIs in melanoma treatment have demonstrated that patients diagnosed with a primary melanoma with inherited MC1R variants have improved melanoma‐specific survival compared to patients with consensus MC1R alleles." (PMID 40926353, 2025). "MC1R germline variants increase melanoma susceptibility, but their prognostic utility in the context of ICI therapy is limited." (PMID 40981345, 2025). "Variants in CDKN2A, CDK4, and MC1R—such as G101W, A148T, and R24C—have been associated with melanoma in populations from Poland, Spain, and the United Kingdom (UK) as well as in Brazilian and Austrian populations." (PMID 40429816, 2025). "Certain MC1R germline genetic variants (R alleles) result in deficient melanin production and are associated with red hair, freckling, UV sensitivity, and melanoma susceptibility." (PMID 40926353, 2025). "While MC1R has been implicated as a major factor for melanoma susceptibility, its impact on survival from metastatic melanoma and treatment efficacy remains unexplored." (PMID 40926353, 2025). "The aim of our study was to evaluate if inherited MC1R R alleles are predictive of the efficacy of immune checkpoint inhibitors (ICIs) in melanoma patients." (PMID 40926353, 2025). "It is well established that red hair color (RHC) individuals contain variants of MC1R that are associated with an elevated risk of skin damage progressing to melanoma." (PMID 40004137, 2025). "These variants are associated with reduced MC1R function and altered melanin synthesis, contributing to an increased risk of developing melanoma." (PMID 41002740, 2025). "According to this finding, a multigene panel testing has been recently carried out on a large Dutch population, showing that MC1R risk variants had a strong association with the melanoma respect to the control group." (PMID 40869905, 2025). "MC1R was included in the genetic panel due to its association with low-to-moderate penetrance risk for melanoma, particularly in individuals with a red hair phenotype, fair skin, and increased UV sensitivity." (PMID 40863406, 2025). "Certain MC1R polymorphisms are considered as genetic risk factors for melanoma, a type of skin cancer." (PMID 41002740, 2025). "In the context of melanoma, carriers of MC1R R alleles tend to present with larger, hypopigmented melanomas, often described as red melanomas." (PMID 40558591, 2025). "The ASIP gene inhibits MC1R shifting melanin color to a less protective isoform; this gene has also been associated to high-risk phenotype and melanoma susceptibility." (PMID 40869905, 2025). "Other MC1R-associated conditions, many with dermatological manifestations, show varying correlations with melanoma." (PMID 40680165, 2025). "Recent studies have found that the PPAR family induces enhanced melanogenesis in melanocytes and melanoma cells by affecting the melanocyte-stimulating hormone receptor (MC1R) and melanocyte-associated transcription factor (MITF) signaling pathways." (PMID 38159176, 2024).
melanoma (continued). "Since, compared with eumelanin, pheomelanin has a weak shielding capacity against ultraviolet (UV) radiation harmful effects, MC1R variant carriers are commonly associated with increased susceptibility to develop melanoma, as described subsequently." (PMID 39334716, 2024). "The melanocortin-1-receptor (MC1R) gene is the most common low risk susceptibility gene for melanoma, mutated in 70–90% of familial melanoma." (PMID 38473375, 2024). "Melanocortin receptor 1 (MC1R) is a G protein-coupled receptor originally found in melanocytes, which has been well-investigated in regulating pigmentation, UV responses, and melanoma risk." (PMID 38433184, 2024). "Many natural human MC1R variants occur and the carriers of MC1R variants, in particular those with pale skin, freckles and red hair, have an around 60% higher risk of developing melanoma." (PMID 38672543, 2024). "MC1R activation lessens T-cell infiltration in the tumor microenvironment and causes a melanoma-specific mechanism of checkpoint blockade therapy resistance and immune evasion." (PMID 38473275, 2024). "Germline mutations of CDKN2A, CDK4, TERT, and POT1 genes have been identified as high-risk factors for melanoma susceptibility, whereas MC1R (melanocortin 1 receptor) polymorphic variants are reported in 60.5–82.1% of melanoma." (PMID 38473275, 2024). "Many MC1R variants confer an elevated risk of melanoma, squamous cell carcinoma, and/or basal cell carcinoma, and a large proportion of individuals of European ancestry carry at least one higher-risk MC1R variant." (PMID 39682213, 2024). "Accordingly, independent of skin type and hair color, some genetic variants of MC1R confer susceptibility also to non-melanoma (basal cell carcinoma, BCC, and squamous cell carcinoma, SCC) skin cancer." (PMID 38473275, 2024). "For example, genes in cluster 2 (SPIRE2, SPATA2L), 3 (OCA2, DBNDD1, FANCA, GAS8) and 4 (URAHP, DEF8, CPNE7, MC1R) underlie the associations between melanoma and pigmentation traits." (PMID 38308491, 2024). "These MC1R variants are common in fair-skinned European populations and are strongly associated with red hair, fair skin, and increased melanoma risk." (PMID 36834954, 2023). "Common variants of the MC1R gene coding the α-melanocyte stimulating hormone receptor are associated with light skin, poor tanning, blond or red hair, and increased melanoma risk, due to pigment-dependent and -independent effects." (PMID 37762683, 2023). "Future studies should seek to investigate how MC1R variants interact with other genetic and environmental risk factors in determining melanoma risk among Brazilian melanoma-prone families." (PMID 37958811, 2023). "Accordingly, the association of variant MC1R alleles and increased melanoma risk relies, at least partially, on this pigmentation-dependent effect." (PMID 37762683, 2023). "have shown that having more than 20 large naevi (≥5 mm diameter) associated with MC1R R/R genotype increase up to 25-fold the melanoma risk, compared with people with zero to four nevi and MC1R WT/WT genotype." (PMID 37895483, 2023). "A recent study carried out in Turkey corroborated the importance of the MC1R genotype in countries with a low incidence of melanoma and mixed population in determining the melanoma risk." (PMID 37958811, 2023). "Although MC1R activation is a melanoma-specific mechanism of immune evasion, hotspot mutations constitutively activating GNAS are found in diverse cancer types." (PMID 37714844, 2023). "MC1R variants are associated with an increased risk of developing melanoma, especially the R variants, which are highly associated with red hair color phenotype." (PMID 37958811, 2023).
melanoma (continued). "An extensive body of research shows that inactivating variants of MC1R are the main contributors to the increased risk of melanoma development, because the functions of UV protection and DNA damage repair are lost." (PMID 37608347, 2023). "Melanoma is associated with red hair and fair skin, which is the phenotype of the (melanocortin 1 receptor) MC1R gene polymorphisms." (PMID 37629650, 2023). "Studies reported that people with certain MC1R variants are at an increased risk of developing melanoma, and that this increased risk is more pronounced in people with CDKN2A mutations." (PMID 37504268, 2023). "Red hair and fair skin in people are usually due to loss-of-function MC1R variants and are associated with accelerated skin aging, as well as increased melanoma risk." (PMID 38110615, 2023). "Genetic variants in the MC1R gene are the most prevalent melanoma genetic risk factor in the white population." (PMID 37895483, 2023). "UVB radiations are more prone to causing melanomas when compared to UVA due to the capacity of UVB to regulate the melanocortin 1 receptor (MC1R) expression, and melanocyte pigmentation." (PMID 36649046, 2023). "The risk of developing melanoma appears to be higher as the number of MC1R variants increase in the carrier; it doubles in subjects with a single variant and can go as high as six times in an individual with two or more variants." (PMID 37895483, 2023). "The risk of developing melanoma appears to be higher as the number of MC1R variants increases in the carrier, doubling in carriers of a single variant and rising to six times in those with two or more variants." (PMID 37568588, 2023). "Red hair phenotype acquired melanocytic nevi and melanocyte-stimulating hormone receptor (MC1R) alleles all independently increase melanoma risk." (PMID 36788900, 2023). "The proband carrying the GPV in the BAP1 gene (MH20) also showed an RHC variant of MC1R (R/0) and had multiple nevi, fair skin, and a history of sunburn in childhood, as well as multiple melanomas diagnosed at an early age." (PMID 37958811, 2023). "A recent study reported that MC1R genotype and nevi number concur synergistically to melanoma risk, and the R/R genotype combined with high nevi count results in a deeply high-risk outline for melanoma." (PMID 37958811, 2023). "Whereas MC1R activation is restricted to melanoma, GNAS activation by hotspot mutations is observed across diverse cancer types and is associated with reduced CXCL9/10/11 expression." (PMID 37714844, 2023). "The low frequency of germline pathogenic variants in the high-penetrance genes and the high prevalence of MC1R variants found in our cohort show the importance of the MC1R genotype in determining the risk of melanoma in the Brazilian melanoma-prone families." (PMID 37958811, 2023). "Higher MC1R expression was associated with worse 10-year survival in primary melanomas (p = 0.0031) and metastatic melanoma (p = 0.0343)." (PMID 37790306, 2023). "To visually assess the association between MC1R and survival, we dichotomized scores by the median value of all malignant melanoma and performed Kaplan–Meier analysis using log-rank statistics." (PMID 37790306, 2023). "Genetic polymorphisms resulting in loss-of-function variants of the melanocortin 1 receptor (MC1R) gene are associated with an increased risk of melanomas." (PMID 36901857, 2023). "Accordingly, deficient cAMP signaling downstream of variant MC1R should impair NER-mediated clearance of DNA lesions caused by UVB, a notion fully supported by extensive analyses of the mutational burden in melanomas of WT or variant MC1R genetic background." (PMID 37762683, 2023). "By in vivo CRISPR screening in B16F10 melanoma in female mice, here we report that loss of melanocortin-1 receptor (MC1R) in melanoma cells activates antitumor T cell response and overcomes resistance to ICB." (PMID 37714844, 2023).